CD36 (CD36 molecule (CD36 blood group))
Diseases named in the same sentence as CD36 in open-access papers (continued):
Sharing a sentence is not in itself a finding about the gene and the disease.
tumor (continued). "In addition, the FA receptor CD36 can transport fatty acids into cells and affect tumor cell growth, metastasis, and epithelial-mesenchymal transition." (PMID 35833121, 2022). "Similarly, TSP-2, which belongs to the same TSP family of stromal cell proteins as TSP-1, is also a potent inhibitor of tumor angiogenesis, and its binding to CD36 inhibits tumor angiogenesis." (PMID 36354702, 2022). "Furthermore, studies indicated that expression of CD36, a type of scavenger receptor, was elevated on tumor-infiltrating Tregs and CD8+ T cells." (PMID 36003387, 2022). "On the other hand, endothelial cell CD36 may have anti-tumor activity by interfering with tumor angiogenesis." (PMID 35438721, 2022). "Studies have suggested that CD36 may promote tumor growth, metastasis, chemotherapy resistance, and resistance to checkpoint inhibitor immunotherapy, and that CD36 could be a therapeutic target in cancer." (PMID 35438721, 2022). "We have shown that CD36 is downregulated in primary FBs when cocultured with tumor epithelial cells or incubated with the recombinant protein activin A in a dose-dependent manner (2.25 ng/mL to 20 ng/mL) with the proper controls (e.g., activin A neutralizing antibody)." (PMID 36361532, 2022). "Moreover, CD36high cells isolated from CRC patient-derived xenografts have high survivin expression and formed larger tumors than CD36low cells derived from the same tumor, indicating that CD36 also plays a role in CRC cell survival and/or proliferation." (PMID 36568966, 2022). "Interestingly, Treg lymphocytes easily adapt to a lactic acid-enriched TME by CD36 upregulation, and are more resistant to oxidative stress-induced cell death than other T-lymphocyte subtypes, which would imply greater tumor tolerance in these TMEs." (PMID 34356862, 2021). "Inhibition of FAO by genetically ablating CD36 was shown to suppress tumor‐promoting TAM activity." (PMID 34766135, 2021). "Additionally, with regard to T-stage, we saw that 67% had a small tumor size (pT1 and pT2) in the low CD36 group, compared to only 44% in the high CD36 group." (PMID 34439279, 2021). "CD36 expression was negatively correlated with tumor neoantigen burden in most cancer types." (PMID 34234847, 2021). "Since downregulation of CD36 is one of the CAF markers, it is plausible that the tumor microenvironment can be reprogrammed by factors secreted by the CD36+ FBs to induce tumor suppression and, in turn, decrease the production of activin A per our earlier findings." (PMID 34572749, 2021). "Finally, our data indicated that CD36-mediated LCFA mobilization from WAT stimulated tumor growth and enabled resistance to chemotherapy." (PMID 34314388, 2021). "These experimental data confirmed the role of CD36 in HCC tumor progression in vivo." (PMID 33771982, 2021). "Other studies have shown CD36 to be anti-angiogenic via thrombospondin-1 signaling, leading to apoptosis in normal EC, or by blocking the vascular endothelial growth factor receptor 2 pathway in tumor EC." (PMID 34888367, 2021). "Beyond that, regulation of CD36 expression may also involve in other processes of tumor development, such as tumor angiogenesis and tumor immunity." (PMID 33771982, 2021). "However, in a harsh TME, tissue-resident memory (Trm) cells are prone to take in FAs via CD36 to support the anti-tumor response and their long-term survival." (PMID 34742349, 2021). "Both tumor size and tumor weight were lower in CD36 EC-KO mice compared with WT littermates." (PMID 34314388, 2021). "CD36 expression has been also reported in tumor cells, stromal and immune cells in tumor tissues." (PMID 34484199, 2021). "Besides, in the same work, Aguirre and colleagues have seen that this fusion depends mainly on the expression of CD36 in CSCs since it is capable of adapting tumor cells to microenvironmental conditions, especially related to energy supply." (PMID 34071445, 2021).
tumor (continued). "Although ABT-510 does not significantly inhibit fatty acid uptake, future TSP1-derived therapeutic agents that potently inhibit CD36 fatty acid transport could enhance anti-tumor immunity and improve T cell-targeted combination therapies." (PMID 33925464, 2021). "CD36 is known as a transmembrane glycoprotein and is expressed in various tumor types." (PMID 34348794, 2021). "Moreover, tissues with high MD, as well as tumor epithelial cells, secrete activin A, which is known to downregulate CD36 in FBs in ex vivo samples as well as 3D models of MD." (PMID 34572749, 2021). "Second, we have performed a cross-sectional analysis of CD36 and tumor stage." (PMID 34439279, 2021). "However, in a low-glucose and high-lactate tumor environment, Tregs are able to oxidize lactate to pyruvate and to upregulate CD36 expression to oxidize lipids." (PMID 34885023, 2021). "However, CD36 is relevant not only to provide FA in cancer cells, but also sustains tumor-supportive MDSCs, Tregs and M2 macrophages." (PMID 34203535, 2021). "CD36 mediates the absorption of fatty acids, the major nutrients for the tumor." (PMID 33809784, 2021). "Furthermore, we explored the downstream signaling pathways by which CD36 mediates glycolysis and tumor growth." (PMID 33771982, 2021). "CD36 has reemerged in anti-tumor therapy as an immunotherapy target on macrophages and T cells." (PMID 33925464, 2021). "Palmitic acid or a high‐fat diet can enhance the metastatic ability of CD36+ tumor cells." (PMID 34977870, 2021). "Furthermore, UVA exposure increased the expression of CD36/SR-B2, a long-chain fatty acid translocator that is related to the metastatic behavior of tumor cells." (PMID 33917064, 2021). "Our results showed that mTOR signaling pathway could be activated by CD36 in HCC and inhibition of mTOR eliminates CD36-mediated glycolysis and tumor-promoting effects." (PMID 33771982, 2021). "TAMs tend to uptake more lipids via CD36 from the TME to sustain their tumor-promoting ability." (PMID 34742349, 2021). "Indeed, lipotoxicity was observed in tumor bearing mice treated with the CD36-neutralising antibody." (PMID 34215227, 2021). "CD36 ablation severely decreases lipid uptake in Tregs, leading to a deceleration in tumor growth." (PMID 34742349, 2021). "Targeting the LPA/PKD-1 -CD36 signaling pathway may have therapeutic potential to curb tumor progression by disrupting the arteriolar niche and effectively eliminating CSCs." (PMID 34168243, 2021). "The tumor incidence in CD36 overexpression group (five in nine mice) was higher than the control group (one in eight mice), but we did not observe the evident of tumor volume variation between the two groups of SK-Hep-1 tumors, probably because of the low number of the control tumors." (PMID 33771982, 2021). "Interestingly, in the clinical datasets explored, FABP4 was the most common protein correlating with increased CD36 expression in 15 out of the 16 tumour types assessed." (PMID 34561446, 2021). "For example, CD36 binds thrombospondins, which mediatecell adhesion and migration by regulating cell-to-cell and cell-to-matrix interactions.Specifically, CD36 modulates the thrombospondin antiangiogenic activity, which hasobvious implications on tumor growth." (PMID 34603769, 2021). "Likewise, both constitutive and tumor cell debris-induced expression of CD36 was downregulated in the ZnPP-treated macrophages." (PMID 33809707, 2021). "In addition, CD36 targeting induced additional anti-tumor responses with anti-PD-1 therapy through enhancement of anti-tumor activity in tumor-infiltrating lymphocytes." (PMID 33413697, 2021). "It was suggested that low expression of CD36 might reduce tumor cell adhesion to the extracellular matrix, followed by an increase of cell mobility due to decreased ability of CD36 to bind collagen." (PMID 32781778, 2020). "CD36 is notably upregulated in Tregs, especially in those found in the tumor microenvironment." (PMID 33086598, 2020).
tumor (continued). "Altogether, the evidence available suggests that tumor heterogeneity may account for the diversity of mechanisms by which CD36 promotes metastasis in different tumor types." (PMID 33232276, 2020). "CD36 is a cell adhesion receptor and it was reported that it could modulate the vascularization of tumor tissues." (PMID 33102231, 2020). "CD36/caveolin-mediated endocytosis is the main internalization mechanism and might be effective also in tumour cells." (PMID 32397484, 2020). "Moreover, consistent with our in vitro data, qRT-PCR analysis of tumor tissues demonstrates a decrease in survivin expression when CD36 is knocked down in HT29 LuM3 tumors." (PMID 32850342, 2020). "This decrease in CD36 is particularly meaningful, since a similar downregulation of CD36 expression is observed in CAFs compared to fibroblasts from healthy reduction mammoplasty tissue, thus suggesting that it can be an early event in tumour formation." (PMID 32178425, 2020). "Moreover, in recent decades, numerous studies have concluded that CD36 plays a role in accelerating tumor growth, metastasis, regulating chemoresistance and radioresistance, modulating tumor immunity, etc.." (PMID 33364199, 2020). "CD36 is a scavenger receptor that allows cells to take up triglycerides and use them to support fatty acid oxidation, and its expression has been shown to support tumor-promoting M2 macrophages." (PMID 32469992, 2020). "The fact that basal-TNBC and CL-TNBC tumours had similar expression levels of MYC yet very different expression levels of CD36, LPL, PDK4 and FABP4 suggested that there are likely other factors, besides MYC, that direct activation of FAO and lipid metabolism in CL-TNBC." (PMID 31942031, 2020). "Intravesicular cargo of microvesicles transferred to immune cells via CD36 can persist in these cells for extended time periods, and, thus, CD36 could potentially support the long-term reprogramming of cellular phenotypes relevant for tumor metastasis." (PMID 32781778, 2020). "Cancer cells are characterized by higher rates of lipid biosynthesis in addition to increased glycolysis and lactate production than those of normal cells as well as high fatty acid uptake that require the expression of CD36, over-expressed in the majority of tumor tissues." (PMID 33013380, 2020). "Consistently throughout this study, we observed that the higher expression of CD36 in HT29 LuM3 cells as compared to parental HT29 cells, makes these cells more sensitive to CD36 inhibition via CD36 shRNA and inhibits xenograft tumor growth to a higher extent as compared to HT29 xenografts." (PMID 32850342, 2020). "CD36 mediates the FA uptake, key nutrients for tumor metabolism." (PMID 32781778, 2020). "Considering the existence of miR-LDL complexes and ongoing tumor cell apoptosis, we asked whether MΦ CD36 might be involved in “miR-375-LDL” uptake." (PMID 30850595, 2019). "Because CD36 is at the top of the signaling cascade that removes lipids from the extra-cellular environment, we chose to determine whether the tumor-promoting effects of PA were mediated by CD36 by assaying for wound-healing, cell migration and invasiveness." (PMID 30717785, 2019). "Apoptotic tumor cells also release various factors including long-chain free fatty acid and oxidized phospholipid, which may also act as a carrier of miR-375 for CD36-mediated uptake, as they are known ligands of CD36." (PMID 30850595, 2019). "CD36 mediates the uptake of FAs, which are key nutrients for tumor metabolism." (PMID 31410189, 2019). "Because inflammation triggers the initiation, proliferation, invasion, and metastasis of tumor cells, reducing CD36-mediated sterile inflammation might provide the basis for a new mode of antitumor treatment." (PMID 31410189, 2019). "Finally, siRNA silencing of CD36 largely prevented tumor-derived miR-375 uptake by recipient macrophages." (PMID 31766495, 2019).
tumor (continued). "In CRC cells, CD36 acts as a tumor suppressor and inhibits aerobic glycolysis in vitro and in vivo." (PMID 31484922, 2019). "The results confirm that ACM promotes the upregulation of cell surface-associated CD36 for both tumor cell lines but not in normal mammary cells." (PMID 31847105, 2019). "Importantly, studies have shown that CD36 can serve as an effective marker to isolate tumor cells with high metastasis-initiating potential from multiple cell lines and plays a significant role in cancer development through different mechanisms 35-37." (PMID 31410220, 2019). "Thus, TSP-1 and TSR associate with CD36 and trigger MVEC apoptosis and block VEGF signaling and thereby inhibit tumor growth." (PMID 31410189, 2019). "In addition, Kaplan-Meier survival analysis showed that patients with high CD36 expression level in tumor tissues had poorer prognosis than those with lower CD36 expression using our own cohort (P = 0.0033)." (PMID 30717785, 2019). "Hence, our results suggested GPC4 was indispensable for CD36-mediated tumor-suppressive functions in CRC cells." (PMID 31484922, 2019). "Genes related to lipid metabolism and immune response that are associated with poor prognosis were discovered including HMGCS2, GPX2 and CD36, which may provide clues for tumor biomarkers or therapeutic targets." (PMID 31074374, 2019). "Thus, through its role in mediating the uptake of exogenous FAs, CD36, as the surface receptor of FAs, mediates the tumor-promoting effect of PA both in vitro and in vivo." (PMID 30717785, 2019). "CD36 is responsible for lipid uptake to trigger downstream inflammatory signaling in innate immune cells, and it has been reported that lipid deposition in dendritic cells inhibits antigen cross-presentation and dampens anti-tumor immune response." (PMID 31847240, 2019). "Taken together, these data supported the tumor-suppressive roles of CD36 in CRC cells." (PMID 31484922, 2019). "While both CD36+ and CD36- cells were able to form primary tumours, only the CD36+ population produced metastasis; administration of two different neutralizing antibodies against CD36 completely inhibited metastasis formation or their size and number when metastasis where already established." (PMID 31922096, 2019). "However, there seemed to exist more complex roles for CD36 regarding tumor development and progression." (PMID 31484922, 2019). "Several preclinical and clinical studies recently demonstrated that upregulation of CD36 could be a prerequisite for tumor metastasis, opening new avenues for anticancer therapies." (PMID 31379931, 2019). "These amazing research findings highlight the critical role of CD36 in promoting tumor metastasis." (PMID 31655604, 2019). "Only one study has focused on the DNA methylation status of CD36 in relation to tumor progression." (PMID 31379931, 2019). "Interestingly, the enhancement of PTEN and CD36 and the reduction in Snai1 and Zeb1 mRNA expression in the tumor tissue by ApoSQ injection were reversed by GW9662 treatment." (PMID 30842627, 2019). "Elevated lipid deposition and inflammatory factors in tumor tissues might induce and alter CD36 expression and distribution, and this could contribute to a high metastatic rate." (PMID 31410189, 2019). "Mechanically, the tumor-suppressive effects of CD36 were mediated through promoting the proteasome-dependent ubiquitination of GPC4, and the degraded GPC4 failed to activate β-catenin/c-myc signaling cascades and downstream glycolytic target genes GLUT1, HK2, PKM2 and LDHA." (PMID 31484922, 2019). "Thus, CD36 facilitates the migration and recruitment of TAMs in tumor tissues, which promotes tumor progression." (PMID 31410189, 2019). "Herein, GPC4 was reported to be an indispensable downstream effector of CD36 and ectopic GPC4 expression could reverse the tumor suppressive and glycolysis inhibitory functions of CD36 by activating β-catenin/c-myc signaling in CRC cells." (PMID 31484922, 2019).
tumor (continued). "Moreover, down-regulation of CD36 led to severe inhibition of rCOMP-induced tumor growth and lung metastasis of HCC in vivo." (PMID 30231922, 2018). "Nobiletin also inhibited CD36-dependent tumor migration, invasion, and tumor sphere formation." (PMID 29914089, 2018). "Fatty acid transporter CD36 is also indispensable in the process of tumor metastasis." (PMID 30013512, 2018). "Nobiletin also inhibited CD36-mediated tumor sphere formation." (PMID 29914089, 2018). "However, blocking CD36 in a tumour system composed of tumour cells and stromal niche would equally affect both populations." (PMID 30069479, 2018). "In addition, a parallel analysis of stromal CD36 versus tumour CD36 is usually missing from the scientific argument in most original articles." (PMID 30069479, 2018). "CD36 is considered to be a major factor in tumor metastasis." (PMID 29914089, 2018). "In addition, several groups reported that CD36-mediated FA uptake plays a role in the pathogenesis of various neoplasms." (PMID 29765537, 2018). "Recent research shows that CD36 plays a role in tumor metastasis by mediating lipid metabolism." (PMID 29914089, 2018). "Several studies have focused on the identification of candidate genes in mouse models of FAP (known as MOM - modifiers of MIN), reviewed in and recently 7 potential modifier genes (CD36 being one of them) have been identified that affect tumour multiplicity in this model." (PMID 30065793, 2018). "We showed that CD36 has a role in tumor migration and invasion, which are key for metastasis." (PMID 29914089, 2018). "A common denominator of most stromal partners in tumour progression is CD36, a scavenger receptor for fatty acid uptake that modulates cell-to-extracellular matrix attachment, stromal cell fate (for adipocytes, endothelial cells), TGFβ activation, and immune signalling." (PMID 30069479, 2018). "Additionally, dietary fatty acid exposure increased tumor cell expression of CD36 and increased metastasis in mice." (PMID 29697773, 2018). "CD36 neutralizing antibodies were shown to eliminate lymph node metastasis in mice that were inoculated with tumor cells, suggesting that it may also be applicable in treatment of CLL-affected lymph nodes." (PMID 29765537, 2018). "Vstat120 has a tumor-suppressive effect during the intracranial growth of malignant gliomas, which is accompanied by a decrease in the tumor vascular density both in vitro and in vivo via CD36: a cell surface receptor on endothelial cells." (PMID 30513696, 2018). "Next, we investigated the role of CD36 in tumor sphere formation." (PMID 29914089, 2018). "To determine whether a similar correlation exists in vivo, we compared Fabp4 and Cd36 levels in TAMs isolated from MMTV-PyMT tumor-bearing mice with peritoneal macrophages isolated from the same mice." (PMID 28974683, 2017). "Intriguingly, CD36 also appeared to express in a few tumor cells in DIO mice." (PMID 28186980, 2017). "Tumor associated endothelial cells (TAECs) exposed to LPA demonstrated sustained nuclear PKD-1 phosphorylation, and elevated mRNA levels of ephrin B2, and reduced mRNA expression of CD36." (PMID 28186980, 2017). "CD36 downregulation in the tumor endothelium could be a key step that initiates the microvascular remodeling for de novo tumor arteriogenesis." (PMID 28186980, 2017). "Loss of stromal CD36 expression in-vitro and in-vivo resulted in less fat accumulation and greater ECM accumulation, a phenotype shared by tissues of high MD and desmoplastic tumour stroma." (PMID 26784251, 2016). "However, considering that TSP-1 protein levels in tumor and surrounding tissue are found to be elevated in several cancers, one can assume that CD36-activating concentrations are reached within a tumor microenvironment." (PMID 26578962, 2015). "Cd36 was downregulated approximately twofold in whole metastatic tumours from each model." (PMID 25633981, 2015).